PIN1 (peptidylprolyl cis/trans isomerase, NIMA-interacting 1)
Diseases named in the same sentence as PIN1 in open-access papers (continued):
Sharing a sentence is not in itself a finding about the gene and the disease.
tumor (continued). "Through multiple regulatory mechanisms, Pin1 promotes tumor initiation, development, and drug resistance by acting as an activator of some oncogenes and growth enhancers, or as an inactivator of some tumor suppressors and growth inhibitors." (PMID 32296699, 2020). "Emerging evidence has suggested that Pin1 promotes tumor initiation and progression by activating oncogenes." (PMID 33024085, 2020). "Loss of PIN1 also renders cells resistant to transformation and, strikingly, PIN1 knockout mice have delayed tumor formation when crossed with tumor-driving mutants of HER2 or RAS." (PMID 32300594, 2020). "Alongside the tumor-promoting function, Pin1 has also been suggested to bear conditional tumor suppressor activity." (PMID 31884567, 2020). "The prolyl isomerase Pin1 is a pivotal catalyst for tumour progression that involves proline-directed phosphorylation." (PMID 32010480, 2020). "Inhibition of apoptosis by PIN1 results in an increase of tumor growth in HCC xenograft mouse model." (PMID 32010690, 2019). "As a result, co-expression of PIN1 and HBx synergistically promotes cell proliferation and xenograft tumor growth in HCC as compared with the expression of PIN1 or HBx alone." (PMID 32010690, 2019). "By impairing pre-miRNA binding capacity of XPO5, PIN1 has been found to reduce the expression of tumor suppressive miRNAs, such as miR-122, miR-200b, and miR-146a." (PMID 32010690, 2019). "We next examined the correlation of tumor level of Pin1, RhoA and RhoC transcripts with the clinicopathological parameters of the HCC patients." (PMID 31324164, 2019). "The human homolog of Pin1 is overexpressed in breast cancer, increases the transcriptional activity of c-Jun and promotes tumor growth." (PMID 31157221, 2019). "In comparison with slow-releasing ATRA formulation, the treatment of ATRA-PLLA microparticles shows a more significant inhibition of xenograft tumor growth and reduction of PIN1 protein expression." (PMID 32010690, 2019). "Through decreasing the expression of these miRNAs in HCC cells, PIN1 promotes cell proliferation in vitro and tumor growth in vivo." (PMID 32010690, 2019). "Next, we detected Pin1 and ERα protein levels in tumor tissues of recurrent ER positive breast cancer patients, who have received tamoxifen treatment." (PMID 31867329, 2019). "To study the long-term effect of the silencing of PIN1 and PTOV1 on cell proliferative potential, we performed colonogenic assay which is associated with tumor formation in vivo." (PMID 31083670, 2019). "PIN1-mediated peptidyl prolyl cis-trans isomerization activates, or inactivates, multiple oncogenes and tumor suppressors, respectively." (PMID 30314361, 2018). "Pin1 also downregulates other tumor suppressors, including Kruppel-like factor 1085, suppressor of variegation 3-9 homolog 186, and CDK1087." (PMID 30158600, 2018). "Altogether, these results feature PIN1 as a tumor promoter, but Yeh and Means described PIN1 as a “conditional” tumor suppressor and successive studies support this theory." (PMID 30723410, 2018). "Pin1 is involved in many cellular processes, the aberrance of which lead to both degenerative and neoplastic diseases." (PMID 30158600, 2018). "As a major regulator of oncoproteins, Pin1 amplifies oncogenic pathways by activating more than 43 oncogenic molecules and suppressing at least 20 tumor-suppressing molecules, including many of which have well-established roles in CSCs." (PMID 29848341, 2018). "We also compared PIN1 levels in mouse Brca1 tumor cells and normal mouse mammary epithelium and confirmed that PIN1 levels were significantly higher in the tumor cells." (PMID 30590041, 2018).
tumor (continued). "Numerous oncogenes and tumor suppressors are directly regulated by PIN1, and here we show that PIN1 is an important contributor to LYN hyperactivation in BRCA1 mutant tumor cells." (PMID 30590041, 2018). "Co-immunoprecipitation (coIP) demonstrated that in mouse Brca1 null tumor cells, PIN1 interacted with LYN." (PMID 30590041, 2018). "Our results showed that doxycycline-induced Pin1 KD significantly suppressed tumor growth in both HL-60 and U937 Pin1 KD cells with reductions of both tumor weight and tumor volume exceeding 50%." (PMID 29848341, 2018). "In this present study, we showed that Pin1 expression is down regulated upon sorafenib treatment and inhibition of Pin1 either by genetic or chemical ablation potentiates anti-tumor efficacy of sorafenib against HCC in vitro and in vivo." (PMID 28404959, 2017). "The tumor growth was significantly suppressed after Pin1 knockdown, as illustrated by the tumor growth curve and tumor weight n = 9, P = 0.035)." (PMID 28262728, 2017). "PIN1 inhibitors such as juglone, PiB, and all-trans retinoic acid have been used successfully in in-vitro studies to inhibit tumour growth, supporting the role of PIN1 as a potential therapeutic target." (PMID 28076852, 2017). "In this study, we identified miR-874-3p as a tumour suppressive miRNA that down-regulated PIN1 expression in HCC." (PMID 28076852, 2017). "Genetic ablation of PIN1 reduces tumour growth and metastasis in several oncogene-induced mouse models of tumorigenesis, indicating the requirement for PIN1 for the development and progression of some tumours." (PMID 28598431, 2017). "Taken together, our data suggested that miR-874-3p plays a tumour suppressive role in HCC through down-regulation of PIN1." (PMID 28076852, 2017). "Taken together, these data consistently demonstrate that ATRA synergistically enhances the ability of sorafenib to induce Pin1 down-regulation, cell death and inhibit tumor growth of HCC in vivo." (PMID 28404959, 2017). "By employing the bioluminescence assay, we were able to demonstrate the suppression of HIF-1α transcriptional activation by pharmacologic inhibition of PIN1 in tumor hypoxia." (PMID 26784107, 2016). "Though PIN1 is overexpressed in many human tumors including those formed in prostate, breast, lung, liver, and colon, some investigators have suggested the tumor suppressor function of PIN1." (PMID 26784107, 2016). "Pin1 is widely viewed as a master orchestrator of malignant transformation and tumor progression because Pin1 regulates numerous oncogenes and tumor suppressors." (PMID 27618008, 2016). "PIN1 is crucial in tumor cell transformation, as it activates oncogenic pathways and growth enhancers while inactivating tumor suppressors and growth inhibitors." (PMID 27258148, 2016). "Pin1 expression was significantly higher in tumor tissues than adjacent/normal specimens (52.8% and 17.5%, respectively, P=0.001)." (PMID 28032861, 2016). "Here, we have shown that Pin1 has a critical role in Myc-driven B cell lymphomagenesis in the Eμ-myc transgenic model, in line with its tumor-promoting activity in other cell types and in the context of Ras signaling." (PMID 26943576, 2016). "The in vivo effect of the PIN1 inhibitor on cyclin D1 repression was further confirmed by the intra-tumor injection of Juglone into C666-1 xenografts in nude mice models." (PMID 27258148, 2016). "By investigating the effects of PIN1 expression on EBV-associated NPC, we revealed its contribution to tumor cell growth and tumorigenesis." (PMID 27258148, 2016). "By utilizing a bioluminescence imaging technique, we were able to demonstrate that PIN1 inhibition dramatically reduced the tumor volume in a subcutaneous mouse xenograft model and angiogenesis as well as hypoxia-induced transcriptional activity of HIF-1α." (PMID 26784107, 2016).
tumor (continued). "We show that PIN1 suppression inhibits in vitro and in vivo tumor growth in NPC cells while its overexpression induces the anchorage-independent growth of nasopharyngeal epithelial cells." (PMID 27258148, 2016). "EGCG was shown to suppress the proliferation of cells expressing Pin1 and tumor growth in a xenograft mouse model Pin1." (PMID 27941682, 2016). "Concordant with our PIN1 siRNA study, the depletion of PIN1 suppresses tumor cell proliferation, DNA synthesis and colony formation in NPC cells." (PMID 27258148, 2016). "Pathological grading, TGFBR2, TGF-β, MAPK, pin1, β-catenin in tumor tissue and TGF-β in normal mucosa were ultimately identified as significant prognostic predictors." (PMID 27008710, 2016). "Overexpression of Pin1, however, is attributed to a large number of malignancies at both the tumor and molecular levels." (PMID 25588053, 2015). "The role of the androgen receptor is pivotal, and androgen receptor serine 81 mediates Pin1 interaction and defines tumor grade by modulating androgen receptor function." (PMID 26039047, 2015). "We observed that Pin1 in tumor part was higher in 47 (84%) patients when compared to corresponding non-tumor part." (PMID 25160749, 2014). "In xenograft tumor models, the inhibited tumorigenesis in cells with Pin1 knockdown was partially recovered by cyclin D1 restoration." (PMID 25160749, 2014). "Cells overexpressing Pin1 and Fbxw7α, instead, showed a significant recovery of tumor formation, since tumors grew in seven out of nine mice, a trend that was observed also for the subsequent dilution of 150 000 cells." (PMID 24357640, 2014). "Pin1 can promote tumorigenesis by activating or stabilizing numerous oncoproteins and also inactivating or destabilizing a number of tumor suppressors." (PMID 25160749, 2014). "The fate of several oncoproteins and tumor suppressors was controlled by Pin1-mediated cis/trans isomerization." (PMID 25160749, 2014). "When compared to the corresponding non-tumor part, Pin1 protein and mRNA levels in tumor part were higher in 84% and 62% patients, respectively." (PMID 25160749, 2014). "In xenograft tumor model, we observed that the tumor size from cells with Pin1 knockdown was smaller than that from parental CE81T cells." (PMID 25160749, 2014). "PIN1 expression was significantly correlated with tumor cell proliferation (Ki-67 labeling index; P=0.024)." (PMID 24179535, 2013). "The immunoreactive score for PIN1 was significantly higher in the tumor cells (4.07±0.4) compared with the adjacent benign bile duct cells (1.19±0.4) (P<0.001)." (PMID 24179535, 2013). "Peptidylprolyl isomerase 1 (Pin1), a protein overexpressed in many tumor types including breast, has been demonstrated to modulate ERalpha activity and is involved in resistance to hormonal therapy." (PMID 23390529, 2013). "Previous studies suggested that high expression of PIN1 is correlated with tumor development and poor prognosis." (PMID 24013949, 2013). "Silencing PIN1 gene expression significantly inhibited tumor cell proliferation and decreased the migration and invasion of the ECC cells." (PMID 24179535, 2013). "A significant correlation was identified between the degree of PIN1 expression and the tumor cell proliferation rate (Ki-67 labeling index)." (PMID 24179535, 2013). "The present data revealed that the degree of PIN1 expression was significantly higher in the ECC tissues compared with the non-tumor tissues." (PMID 24179535, 2013). "Silencing PIN1 expression using siRNA significantly decreased the proliferation, migration and invasion of the tumor cells." (PMID 24179535, 2013). "It has also been reported that inhibition of Pin1 function in human tumour cells, using Pin1 antisense RNA, induces mitotic arrest and apoptosis." (PMID 21219594, 2011). "Inhibition of Pin1 via RNAi resulted in significant suppression of Her2-positive tumor cell growth in BT474, SKBR3 and AU565 cells." (PMID 19077306, 2008).
tumor (continued). "Critically, we provide evidence that linking tumor cell-intrinsic Pin1 to stromal reprogramming." (PMID 41246306, 2025). "Moreover, the Pin1 inhibitor reduced p65 expression in subcutaneous tumor tissues in mice, as detected by IHC, indicating Pin1-mediated NF-κB activation." (PMID 41246306, 2025). "The upregulation of NRF2-mediated cytoprotective and phase II detoxifying enzymes, without direct evidence of KPT-6566’s effects on NRF2 protein/mRNA levels and its interaction with PIN1, raises questions about its impact on cellular resistance and promotion of a tumour-supportive environment." (PMID 40087364, 2025). "The PLGA-CpG@ID8-M nanovaccine overcomes free CpG accumulation, reprograms TAMs to tumoricidal M1 macrophages via Gbp2/Pin1–NFκB signaling, inhibits tumor growth, and counteracts chemotherapy-induced immunosuppression by boosting M1 TAMs and lowering tumor CD47." (PMID 41280929, 2025). "Consistent with our hypothesis, the Pin1 inhibitor + aPD-1 group exhibited the slowest tumor growth and the smallest tumor volume, indicating Pin1 blockade enhances immunotherapy efficacy in MSS models." (PMID 41246306, 2025). "PIN1 was stepwise upregulated with N stage and tumour stage." (PMID 37929660, 2024). "Furthermore, AMPNs degrade Pin1 expression whilepromoting PD-L1 upregulation in tumor cells, thereby triggering arobust antitumor immune response and enhancing the efficacy of PD-L1/PD-1immune checkpoint blockade therapy." (PMID 39051165, 2024). "Peptidyl-prodyl cis-trans isomerase 1 (Pin1) is a tumor-specific enzyme." (PMID 38285118, 2024). "Inhibition of either CDK4 or PIN1 has been reported to trigger anti-tumor immunity." (PMID 38622115, 2024). "Further, we demonstrated that a key protein identified from our unbiased approach, peptidyl-prolyl cis/trans isomerase (PIN1), is essential for inducing cellular senescence in fibroblasts and functions by regulating the protein levels of both tumor suppressors and oncogenes." (PMID 38216124, 2024). "The results showed that most USP34-positive tumor cells also had strong Pin1 staining." (PMID 38167292, 2024). "Tissue stainingrevealed tumor damage, Pin1 inhibition, and increased PD-L1 expression." (PMID 39051165, 2024). "Conversely, Pin1 may also disrupt the balance between oncoproteins and tumor suppressors by promoting the degradation of key tumor suppressors." (PMID 38727267, 2024). "Consequently, it is highly desirable to further elucidate the role of Pin1 in mediating the up-regulation of oncogenes, as well as the downregulation of tumor suppressors, which can effectively hinder malignant cell development." (PMID 39624096, 2024). "In addition to juglone, epigallocatechin-3-gallate (EGCG), all-trans retinoic acid (ARTA), and arsenic trioxide (ATO) have shown good efficacy as inhibitors of Pin1 in reducing tumor resistance." (PMID 36770689, 2023). "Moreover, Pin1 directly binds and activates 56 oncogenic proteins and inactivates 26 tumor suppressors." (PMID 37508437, 2023). "We next investigated whether PIN1 could promote tumor progression of TNBC through destabilizing pVHL." (PMID 36813923, 2023). "Ablation of PIN1 effectively suppresses tumor development in Neu or Ras transgenic mice." (PMID 37370134, 2023). "In combination, we propose that in HCC, aberrant L1 ORF1p expression leads to higher expression of cytoplasmic PIN1, which contributes towards dysregulation of a number of oncogenic pathways—including upregulation of TGFβ and NF-κB signalling—that promote tumour invasion and metastasis." (PMID 36707636, 2023).
tumor (continued). "Considering the role of Pin1 in TGCT cell proliferation and its contribution to the aggressiveness of TGCTs, targeting Pin1 could disrupt molecular pathways that drive tumor growth and progression." (PMID 38020885, 2023). "Interestingly, even in Pin1-unbound HBx, overexpression of Pin1 in cell lines leads to tumor growth." (PMID 36393854, 2022). "Therefore, additional studies are required to investigate comprehensive Pin1 functions in tumor-initiating cells and during age-dependent neurodegeneration." (PMID 35433695, 2022). "Furthermore, Juglone and KPT6566 suppress the tumorigenic properties of CD44+CD133+ tumor-initiating Caco-2 cells, demonstrating a critical role for Pin1 in promoting the tumorigenic potential of these cells." (PMID 35433695, 2022). "Thus, targeting Pin1 in CD44+CD133+ tumor-initiating cells is a promising therapeutic approach to treating human CRC." (PMID 35433695, 2022). "Suppression of Pin1 significantly inhibited tumor weight and volume in hyperglycemic mice." (PMID 35461311, 2022). "Finally, in a syngeneic mouse model, IL-36γ-induced tumor growth in the breast mammary gland was significantly inhibited following PIN1 knockout." (PMID 35954317, 2022). "PIN1 is considered as a therapeutic target for a wide variety of tumours." (PMID 34894990, 2022). "Taken together, these data suggest that targeting the Pin1 protein might be a preferential and effective strategy for killing tumor-initiating CRC cells." (PMID 35433695, 2022). "Pin1 plays an important role in the glucose metabolism of tumor cells." (PMID 35461311, 2022). "DNA barcodes on these micellular systems offer an easy-to-change way to customize the targeting demand, opening the way for Pin1 inhibition in certain cell populations of the tumor and thus uncovering mechanistic details on how Pin1 supports tumor initiation and progression." (PMID 35879297, 2022). "The role of PIN1 in tumor-promoting inflammation has been extensively studied." (PMID 35954317, 2022). "In addition to elevating tumor-promoting, Pin1 also upregulates some anti-inflammatory factors, such as NUR77 and glucocorticoid receptor (GCR) to regulate inflammation response." (PMID 33807199, 2021). "However, Pin1 promotes tumorigenesis not only through enhancement of the cell’s proliferating ability but also via other tumor-promoting processes." (PMID 33807199, 2021). "However, Pin1 has been implicated in EBI2-induced Eos migration and TGF-beta-induced migration of tumor cells." (PMID 33494375, 2021). "PIN1 inhibition with specific siRNA or ATRA suppressed tumor growth in PDAC." (PMID 32258027, 2020). "Pin1 and c-Jun statuses according to Age, Lymph node status, Tumor size, P16 and Ki67." (PMID 32010480, 2020). "Overexpression of Pin1 promotes tumor growth, while its inhibition leads to tumor cell apoptosis." (PMID 32518522, 2020). "In addition, the result of a xenograft tumor growth assay in mice utilizing Neu/Pin1 KO and WT MEF cells have been shown similar to the result from the in vitro enzyme assay." (PMID 32258027, 2020). "Pin1 promoted cell metastasis by increasing IL‐18 expression, and the oncogenic effect of IL‐18 was also significantly decreased in Pin1 knockdown cells, which highlighted the role of Pin1 in IL‐18‐induced tumour‐promoting effect." (PMID 32347623, 2020). "Aside from Pin1′s influence over Myc’s stability, there are several other mechanisms in which Pin1 can promote tumorigenesis such as sustaining proliferative signaling and downregulating tumor suppressors." (PMID 33322239, 2020). "Several works suggest that Pin1 is an expert in injuring tumor suppressors." (PMID 32296699, 2020). "In addition, Pin1 also activates many pro-proliferative proteins to enhance tumor cell proliferation and tumor growth, including c-Myc and XPO5." (PMID 32296699, 2020). "Moreover, PRKX binds to enzymes such as Pin-1, Magi-1 and Bag-3, which regulate cell differentiation, proliferation, apoptosis and tumor genesis." (PMID 31964936, 2020).